LEP (leptin)
Diseases named in the same sentence as LEP in open-access papers (continued):
Sharing a sentence is not in itself a finding about the gene and the disease.
metabolic syndrome (continued). "Indeed, several studies have reported that circulating IGFBP-2 was related to insulin sensitivity, metabolic syndrome and antidiabetic effect by regulate the expression of leptin gene." (PMID 31547433, 2019). "During formation of metabolic syndrome this may act in a compensatory way, in which the leptin/adiponectin ratio and a potential imbalance of both mediators is highly critical." (PMID 31293441, 2019). "BMI level was positively correlated with demographic factors (age, male and marriage), underlying diseases (DM, hypertension and dyslipidemia), the mental component summary (MCS) score from the SF-36, and laboratory factors (leptin, TNF-α, HS-CRP, HOMA-IR and WBC count)." (PMID 30013128, 2018). "Moreover, a previous study considered the adiponectin/leptin ratio to be a better inflammatory marker for the metabolic syndrome population." (PMID 29791651, 2018). "The leptin/ApN ratio is now considered to be an indicator of metabolic syndrome." (PMID 30115912, 2018). "Noting that those depressive patients with higher leptin levels also had elevated BMI, it is hard to conclude that leptin is positively linked to depression, rather than a compensatory effect induced by adiposity and metabolic syndrome." (PMID 30367065, 2018). "Also, the leptin/adiponectin ratio, a surrogate marker to assess the metabolic syndrome, was significantly lower in ATKlk7−/− mice under HFD." (PMID 28932870, 2018). "Moreover, Santos and colleagues reported that Mas-knockout mice presented with dyslipidemia, as well as increased levels of insulin and leptin, and that Mas deletion led to glucose intolerance and reduced insulin sensitivity." (PMID 29618822, 2018). "H. pylori infections may also alter host metabolic homeostasis by affecting appetite regulation and energy expenditure through altered balance of ghrelin and leptin secretion, leading to over-eating and metabolic syndrome pathogenesis." (PMID 29543807, 2018). "Studies using other markers of metabolic syndrome such as leptin have demonstrated that after 4–10 weeks of treatment with RUTF, leptin levels are lower than those of normally nourished children and approximately 7 times lower than the threshold for predicting metabolic syndrome." (PMID 30559964, 2018). "Here we consider the links between co-morbid metabolic syndrome and depression, focusing on biomarkers including leptin and ghrelin in combination with assessing gut microbiota composition, as a potential tool to help identify individual differences in depressed population." (PMID 30405455, 2018). "Moreover, patients with metabolic syndrome and multiple sclerosis present with decreased leptin levels after pioglitazone treatment." (PMID 29791472, 2018). "In addition, serum osteocalcin levels were significantly associated with plasma adiponectin levels and inversely related to leptin levels, in the presence of metabolic syndrome." (PMID 29791651, 2018). "The aim of the present work was to study whether the leptin-adiponectin axis may have a pathophysiological role in the increased systemic inflammation and oxidative stress observed in patients with the metabolic syndrome (MS)." (PMID 28747790, 2017). "Thus the LAR levels were significantly higher in metabolic syndrome subjects than in non metabolic syndrome, as well as the levels of leptin." (PMID 28878827, 2017). "Previous studies showed that animals fed during the light phase exhibit an increased body weight and food consumption, alterations in leptin, insulin, corticosterone, glucose, and free fatty acid levels in plasma, fat accumulation, liver steatosis, and metabolic syndrome." (PMID 29375476, 2017). "A number of studies have shown that adipokines (including leptin, adiponectin and resistin) may be involved in the development of the metabolic syndrome and cardiovascular comorbidities." (PMID 29065479, 2017).
metabolic syndrome (continued). "The increased levels of estrogen and leptin in women may be why women tend to be protected from the metabolic syndrome and cardiovascular disease compared to men83." (PMID 28811502, 2017). "Changes in IMTG were associated with visceral and intermuscular fat, metabolic syndrome, insulin and leptin (p<0.05 for all), however, these associations did not remain after adjustment for visceral fat changes." (PMID 29190720, 2017). "IL-6 and leptin activity in hypothalamus could explain co-occurrence of schizophrenia and metabolic syndrome." (PMID 29163240, 2017). "Both insulin and glucose are the major inducers of Srebf mRNA expression, and thus, these results are consistent with previous studies showing that this obesogenic diet induces GDM and metabolic syndrome, as determined by increased maternal circulating insulin, leptin, and triglyceride levels." (PMID 27555877, 2016). "Leptin induces LOX expression in cardiac myofibroblasts and vascular smooth muscle cells (VSMCs), and serum leptin levels have been found to correlate with cardiovascular disease risk and metabolic syndrome." (PMID 28036074, 2016). "Metabolic dysfunction (such as dyslipidemias, hyperlipolysis, and decreased leptin and adiponectin production) and adipocyte abnormalities (such as differentiation block due to blunted expression of key adipogenic transcription factors) are prevalent during HIV infection." (PMID 27117277, 2016). "It is promising that leptin would provide favorable outcomes in CKD patients with dyslipidemia." (PMID 27307101, 2016). "F-PC2 is unique among the metagenes associated with metabolic syndrome (the others being C-PC2 & E-PC2) in that the associated biomarker is involved with glucose regulation (leptin) rather than a marker for dyslipidemia (triglycerides, VLDL)." (PMID 25643280, 2015). "Serum leptin has also been identified as an independent predictor of metabolic syndrome in men." (PMID 26388952, 2015). "Metabolic syndrome is characterized by high levels of inflammatory cytokines and leptin which can promote breast cancer cell growth through various mechanisms, and decreased levels of adiponectin, resulting in lack of downregulation of tumour cell proliferation and inhibition of apoptosis." (PMID 26030767, 2015). "The prevalence of metabolic syndrome and AH increased with higher levels of leptin." (PMID 24981337, 2014). "Although the AD/Lep cohorts globally show many of the same metabolic and transcriptional changes as the UN/Sal cohorts, nevertheless in females metabolic syndrome is only triggered in UN/Sal/HF cohort and is prevented by postnatal leptin treatment (“leptin rescue”) in UN/Lep/HF." (PMID 24447410, 2014). "Acquired leptin resistance, in which leptin levels are chronically elevated and the administration of exogenous leptin is less effective at inducing satiety, is a well-recognized feature of the metabolic syndrome." (PMID 25232724, 2014). "In conclusion, the current study suggests that serum leptin is prospectively associated with the development of metabolic syndrome independent of body adiposity and proinflammatory markers among older women." (PMID 24455217, 2013). "It is now admitted that appropriate leptin levels during neonatal life are required for normal energy balance regulation and hypothalamic development and function, and leptin provided through breast milk was shown to protect against several outcomes related to metabolic syndrome." (PMID 23840890, 2013). "The gender-specific differences in the association of leptin with the risk of metabolic syndrome were not examined in these longitudinal studies." (PMID 24455217, 2013). "Metabolic syndrome as a risk factor for neurological disorders has been a focus of research since the observations that at the molecular level metabolic syndrome is accompanied by dysregulation in the expression of cytokines and chemokines and alterations in the levels of leptin." (PMID 23896654, 2013).
metabolic syndrome (continued). "Further, post-term children displayed other markers of the metabolic syndrome: lower normal nocturnal systolic blood pressure dipping (p=0.027), lower adiponectin concentrations (p=0.005), as well as higher leptin (p=0.008) and uric acid (p=0.033) concentrations." (PMID 23840881, 2013). "We aimed to find a possible role for leptin on dyslipidemia in hemodialysis patients." (PMID 28197438, 2013). "In general linear regression analysis after adjustment for age, sex, hypertension, dyslipidemia, liver function, metabolic syndrome, body mass index, smoking, eGFR, HOMA-IR, and leptin, NAFLD was only negatively associated with Ln SDNN (P<0.05) rather than with Ln rMSSD, Ln HF, and Ln LF." (PMID 23626730, 2013). "Leptin levels have been correlated with the metabolic syndrome and may vary as a function of ethnicity and gender." (PMID 24198811, 2013). "A recent investigation of adult men suggests that the ratio of adiponectin to leptin may be an important indicator of several factors related to the metabolic syndrome." (PMID 24198811, 2013). "It is likely that normal cells must maintain a fine balance between leptin and adiponectin in order to maintain proper cell and tissue homeostasis, and the components of metabolic syndrome appear to disrupt this balance by increasing leptin and decreasing adiponectin levels." (PMID 22295251, 2012). "CRP and leptin may represent useful biomarkers for predicting the onset of cardiovascular disease or metabolic syndrome in Taiwanese adults." (PMID 22533665, 2012). "Elevated leptin and low CRP levels were associated with metabolic syndrome in both men and women." (PMID 22533665, 2012). "In middle-aged subjects, high leptin in men and high CRP in women were significant predictors of metabolic syndrome; those with elevations in both markers had the highest risk of developing metabolic syndrome." (PMID 22533665, 2012). "Leptin concentrations varied in relation to the metabolic syndrome score in both genders." (PMID 22533665, 2012). "Leptin increases in obesity, type 2 diabetes mellitus, hypertension and metabolic syndrome." (PMID 22691465, 2012). "In the present study, leptin and CRP levels were associated with metabolic syndrome score, indicating that high levels of these markers may be predictive of developing metabolic syndrome similarly to that shown for high baseline fasting insulin levels." (PMID 22533665, 2012). "Furthermore, CRP has been related to metabolic syndrome in several studies, and its production is influenced by leptin." (PMID 22533665, 2012). "In addition to cardiovascular disease, CRP and leptin levels are predictive of metabolic syndrome development." (PMID 22533665, 2012). "Further studies are required to determine the exact role of leptin in metabolic syndrome." (PMID 22533665, 2012). "For example, in obese and nonobese Caucasian children, leptin levels were associated with metabolic syndrome." (PMID 21526991, 2011). "However, after further adjustment for BMI, increased odds of metabolic syndrome with increased leptin levels were only observed in men." (PMID 21526991, 2011). "Analysis of leptin as part of routine physical examinations may prove beneficial for early diagnosis of metabolic syndrome." (PMID 21526991, 2011). "aOdds ratio of metabolic syndromes with leptin levels by sex-specific quartiles." (PMID 21526991, 2011). "Although elevated serum leptin is not considered among the diagnostic criteria for metabolic syndrome, it is increased in subjects with metabolic syndrome." (PMID 21526991, 2011). "Therefore, the aim of the present study was to assess leptin levels and evaluate its association with CVD and metabolic syndrome." (PMID 21526991, 2011).
metabolic syndrome (continued). "Thus, the objective of the present study was to assess the association of leptin with metabolic syndrome and CVD risk in Taiwanese adults as well as the predictive value of leptin levels for identifying patients with metabolic syndrome." (PMID 21526991, 2011). "Serum leptin levels are correlated with CVD risk and metabolic syndrome." (PMID 21526991, 2011). "Serum leptin levels could also predict metabolic syndrome; therefore, analysis of leptin as part of routine physical examinations may prove beneficial in the early diagnosis of metabolic syndrome." (PMID 21526991, 2011). "Therefore, the present study was conducted to determine the effect of soy protein (in the form of textured soy protein) and soy nut intake on serum leptin levels in postmenopausal women with the metabolic syndrome." (PMID 21526104, 2010). "Thus, the dietary factor/component (for example carbohydrate restriction) that lowers serum leptin can also improve several indicators of metabolic syndrome such as circulating triacylglycerol and insulin and fat mass." (PMID 19144201, 2009). "Our results showed that children classified as “low leptin/IGF-1/HbA1c” had the highest probability to stay in that group whereas e.g. children from the “normal group” had a non-negligible risk of drifting into the “dyslipidemia/high leptin” group." (PMID 39899498, 2025). "In summary, our findings suggest that LEP rs7799039 and LEPR rs1137101 are associated with the risk of MetS development and metabolic syndrome–related disorders in the Turkish population." (PMID 39136228, 2025). "Furthermore, HFD-induced dyslipidemia contributes to leptin resistance and adiposity; however, the combination of PUFAs and vitamin K2 in GmOLb likely exerts synergistic effects by enhancing lipid metabolism, reducing inflammation, and supporting energy homeostasis." (PMID 40870774, 2025). "Participants without metabolic syndrome showed weaker leptin-MASLD associations (RRR 0.81, 95% CI 0.45–1.46, p = 0.485), while those with metabolic syndrome demonstrated enhanced susceptibility with a significant interaction effect (RRR 1.88, 95% CI 1.03–3.43, p = 0.041)." (PMID 40956476, 2025). "In addition, another study has shown that leptin and other serotonergic 2C receptor genes may be involved in the metabolic syndrome developed in patients with severe mental illnesses such as schizophrenia." (PMID 37238961, 2023). "After 10 weeks of HFD feeding (HF235; 4655 kcal/kg; 37.5% carbohydrate, 27.5% fat, 17% protein), WT mice given 43 μg per day of rcREG3A for 28 days showed improvement in metabolic syndrome and associated traits (changes in lipid profile, leptin, glucose tolerance) not seen in mice given the vehicle." (PMID 36918710, 2023). "Interestingly, the treatment with metformin and pioglitazone, two compounds used for the management of metabolic syndrome, has been shown to increase the adiponectin/leptin ratio and improve the inflammatory profile, coinciding with decreased brain lesions in MS patients and reduced cancer risk." (PMID 37517520, 2023). "However, we cannot rule out contributions from other factors linked to metabolic syndrome such as leptin, triglycerides, and free fatty acids that were altered by CAMKK2 deficiency at 15 weeks but not 30 weeks." (PMID 35741020, 2022). "Leptin mutation and TB lead non-synergistically to a similar metabolic syndrome." (PMID 35933481, 2022). "Firstly, this is a cross-sectional study, and the causal relationship between plasma leptin levels and weight change, glucose, dyslipidemia, HOMA-IR and hs-CRP levels could not be clarified." (PMID 36090349, 2022). "Hence, the supplementation with adiponectin alleviates the metabolic syndrome, IR and steatosis and could antagonize the oncogenic effects of leptin against the liver." (PMID 35355551, 2022).
metabolic syndrome (continued). "Besides, it was observed that Atm-/- mice were insulin resistant, presented lower levels of adiponectin and leptin, had less subcutaneous and interscapular adipose tissue, increased visceral fat level (similar to metabolic syndrome), and glucose intolerance when compared to normal Atm+/+ mice." (PMID 36354755, 2022). "In a study of OA individuals with and without metabolic syndrome (MetS), Liu and colleagues reported that synovium and IFP secreted higher amounts of leptin in patients with MetS." (PMID 35270000, 2022). "It has been hypothesized that leptin may be an important marker in metabolic syndrome." (PMID 34359179, 2021). "Interestingly, obese individuals with leptin gene mutations and thus, lower leptin levels, do not show the typical hypertension shown by individuals with the metabolic syndrome, but rather show hypotension." (PMID 34512392, 2021). "In addition, central leptin induces SNA to regulate cardiovascular system including the baroreflex tone, heart rate, and blood pressure, and leptin-associated chronic overactivation of SNA causes the development of metabolic syndrome." (PMID 33114326, 2020). "By this set of miRNAs, leptin may trigger a whole machinery to regulate adipocyte metabolism, and their dysregulation could potentially lead to IR, chronic systemic inflammation, and metabolic syndrome." (PMID 31408957, 2019). "It has been suggested that in children and adolescents, the leptin-to-Ad ratio could be a better marker for the diagnosis of metabolic syndrome than plasma leptin or Ad levels individually and that this ratio could be a target for early cardiovascular risk prevention." (PMID 31262082, 2019). "When adjusted for confounders (including biometrics- age, height, leptin, 25OHD, osteocalcin, testosterone and social aspects-current smoking, coffee drinking, alcohol use, physical activity), higher OT (> = 0.74 pg/mL) predicted metabolic syndrome (OR: 2.06 (1.33–3.18), p<0.005)." (PMID 29300770, 2018). "Given that mood disorders and metabolic syndromes co-occur and might interact with each other during their pathophysiological processes, increased leptin could be seen as an indirect proxy of metabolic abnormities attached to depression, rather than a pathological mediator." (PMID 30367065, 2018). "Thus, adipocyte-reduction in leptin signaling occurring in aged males may account, at least in part, for the altered insulin signaling and dyslipidemia that these animals experience." (PMID 28744221, 2017). "Higher plasma leptin and lower adiponectin levels are well known features of the metabolic syndrome (MetS)." (PMID 28077136, 2017). "For instance, it has been reported that serum leptin is augmented in obese individuals with metabolic syndrome (MetS) that also show an elevation in the plasma levels of CRP." (PMID 23986664, 2013). "In the present study, higher levels of serum leptin concentrations were positively associated with the risk of developing metabolic syndrome in older women independent of potential confounders, measures of body fat distribution, proinflammatory cytokines, and CRP." (PMID 24455217, 2013). "Thus, CRP and leptin may represent useful biomarkers for predicting the onset of cardiovascular disease or metabolic syndrome in Taiwanese adults." (PMID 22533665, 2012). "Moreover, serum leptin levels were predicative of metabolic syndrome in both sexes." (PMID 21526991, 2011). "Furthermore, serum leptin was associated with metabolic syndrome in obese and nonobese as well as diabetic Korean populations." (PMID 21526991, 2011). "Furthermore, those with metabolic syndrome were more likely to be in the upper leptin quartiles." (PMID 21526991, 2011). "Finally, increased leptin levels were a predictor of metabolic syndrome in men and women." (PMID 21526991, 2011). "Leptin resistance, however, could relate to the hyperinsulinemia of the metabolic syndrome." (PMID 21991518, 2011).